FOXF2 (forkhead box F2)
Diseases named in the same sentence as FOXF2 in open-access papers (continued):
Sharing a sentence is not in itself a finding about the gene and the disease.
cancer (continued). "It is possible that the decreased FOXF2 leads to an imbalance in matrix synthesis/degradation and provides a suitable environment for the growth and metastasis of cancer cells and leads to a worse outcome at last." (PMID 27487137, 2016). "Therefore, the effect of FOXF2 ultimately leads to G1 phase arrest and induces apoptosis of cancer cells." (PMID 40003882, 2025). "Finally, although we demonstrated that Cxcl5 is a major downstream effector of stromal Foxf2 in the RM-1 model, we cannot exclude potential roles of other cytokines in human cancers." (PMID 36369237, 2022). "FOXF2 manipulates downstream pathways and targets as both a pro-oncogenic and anti-oncogenic factor across different types of cancer, suggesting it may be a new potential clinical marker or therapeutic target for cancer." (PMID 33717680, 2021). "Curiously, the role of FOXF2 in cancer is not fully understood." (PMID 33717680, 2021). "The function and abnormal regulation of FOXF2 in multiple cancers." (PMID 33717680, 2021). "Does FOXF2 regulate other cellular behaviors that control cancer progression?" (PMID 33717680, 2021). "While the exact mechanism for FOXF2’s different roles in cancer is unclear, the following may be part of the explanation." (PMID 33717680, 2021). "Here, we show that forkhead box F2 (FOXF2) functions as a master transcription factor for reprogramming cancer cells into an osteomimetic phenotype by pleiotropic transactivation of the BMP4/SMAD1 signaling pathway and bone-related genes that are expressed at early stages of bone differentiation." (PMID 31222004, 2019). "However, other studies have reported a protumorigenic role of Foxf2 in other cancer types, for example by repressing intestinal stem cells and preventing adenoma formation by inhibiting Wnt signaling." (PMID 30285803, 2018). "FOXF2’s various functions suggest that it may be an important target for cancer treatment." (PMID 33717680, 2021). "We further tested whether FOXF2-regulated CTSK secretion by cancer cells induce osteoclastogenesis." (PMID 31222004, 2019). "miR-182-5p is an oncomiR that is overexpressed in several cancer types; it has been reported to inhibit the expression of targets such as FOXF2 (Forkhead box F2) and MTSS1 (Metastasis suppressor-1)." (PMID 37887350, 2023). "However, FOXF2’s biological functions and specific roles in cancer development remain unclear." (PMID 33717680, 2021). "The role of Foxf2 in pre- and post-EMT cells reflects the well-studied dual role of TGFβ in cancer progression." (PMID 30285803, 2018). "We further focused on four key genes (CABYR, FOXF2, TLE4, and CDH1 ) related to proliferation, apoptosis, tumorigenesis, invasion and metastasis of cancer cells." (PMID 28121627, 2017). "silenced FOXF2 gene by treating HCC cells with an interfering RNA and found that it could significantly promote the proliferation and decrease the apoptosis of cancer cells." (PMID 32503970, 2020). "Some of them were reported to be cancer-related genes, such as CCNB1, EZH2, AXIN2, and FOXF2." (PMID 31321712, 2019).
breast (4 papers, 2018 to 2023). "Forkhead box F2 (FoxF2), as a key member of the forkhead box transcription factors, is downregulated through colorectal tumorigenesis and participates in epithelial-mesenchymal interaction, embryonic development, and extracellular matrix synthesis (ECM)." (PMID 37438760, 2023). "Analysis of a lymph node-negative stratified patient subset demonstrates that low Foxf2 expression significantly correlates with early metastasis formation." (PMID 30285803, 2018).
FOXF2 also shares sentences with these, for which no sentence is quoted: hepatocellular carcinoma (3 papers); adenocarcinoma (2); Axenfeld-Rieger syndrome (2); fibrosis (2); infection (2); leukemia (2); asthma (1); atrial fibrillation (1); benign prostatic hyperplasia (1); cardiovascular disease (1); colon cancer (1); congenital heart disease (1); coronary artery disease (1); endothelial dysfunction (1); esophageal squamous cell carcinoma (1); gastroparesis (1); insomnia (1); Insulin resistance (1); leiomyoma (1); leishmaniasis (1); lymph node (1); open-angle glaucoma (1); oral cancer (1); pancreatic adenocarcinoma (1); papillary thyroid carcinoma (1); primary open-angle glaucoma (1); renal carcinoma (1); reproductive tumors (1); rhabdomyosarcoma (1); serous ovarian cancers (1).
A further 1 disease shares a sentence with FOXF2 in 1 paper.